EGFR (epidermal growth factor receptor)
Diseases named in the same sentence as EGFR in open-access papers (continued):
Sharing a sentence is not in itself a finding about the gene and the disease.
tumor (continued). "Moreover, the proportions of CD107a+CD8+ T cells, GZMB+CD8+ T cells, and IFN-γ+CD8+ T cells were significantly increased in the anti-TGF-β treatment group compared with the isotype control group, suggesting that TGF-β blockade enhanced the anti-tumor function of CD8+ T cells in the EGFR-mutated TME." (PMID 39004699, 2024). "Furthermore, prediction of EGFR mutation status by CT imaging could help physicians select the most representative tumor for biopsy when multiple tumors are present." (PMID 38679659, 2024). "The resampling of the tumour can be considered if there are discrepancies between the mutation results from the biopsy and CT findings (based on deep learning, radiomics, and semantic markers); these combined analyses can potentially reduce the chances of missing EGFR mutations in a tumour mass." (PMID 38539465, 2024). "However, in cohort 2, the frequency of EGFR sensitizing mutation and T790M resistance mutation in G1 (10%~19% tumor cellularity ) was significantly lower than in G2 (20%~30% tumor cellularity) and G3 (>30% tumor cellularity)." (PMID 38902688, 2024). "However, according to the findings, this nanobody causes toxicity against EGFR+ tumor cell lines." (PMID 38191571, 2024). "Furthermore, tumor cells carrying EGFR mutations secrete a higher quantity of PD-L1-positive sEVs." (PMID 39062533, 2024). "Thus, in a potential real clinical scenario, ctDNA-associated rechallenge with EGFR inhibitors could be considered following progression to trifluridine-tipiracil plus bevacizumab or an option as third-line treatment if tumor shrinkage is required." (PMID 38592721, 2024). "These mutations result in the constitutive activation of the EGFR pathway, which promotes cancer cell growth and survival; the EGFR-TKIs exert functions by inhibiting the activity of the EGFR tyrosine kinase, thereby blocking this signaling pathway to inhibit tumor growth." (PMID 38397056, 2024). "Furthermore, anti-EGFR therapy induced TMB might contribute to making a tumor susceptible to ICI immunotherapy." (PMID 39080202, 2024). "Moreover, some reports suggest that co-mutation of tumor suppressor genes may be responsible for the differential response to EGFR-TKI therapy; however, the exact mechanism remains unclear." (PMID 39156250, 2024). "In addition, recent preclinical studies have suggested that anti-EGFR resistance may be driven by cancer associated fibroblasts populating the tumor microenvironment, and their secreted factors." (PMID 38711991, 2024). "In addition, analyzing the mRNA and protein levels of PD-L1 in the Cancer Genome Atlas (TCGA) and internal database (Guangdong Lung Cancer Institute; GLCI) revealed lower PD-L1 mRNA and PD-L1 protein expression in the EGFR-mutated NSCLC samples compared with that in the wild-type tumor samples." (PMID 39766230, 2024). "Therefore, they investigated how the risk of resistance to EGFR-targeted therapy in CRC tumor cells could be reduced using a PDX model." (PMID 38966179, 2024). "Additionally, we revealed that the reduction in tumor growth might be linked to the downregulation of proteins involved in tumor progression like EGFR and STAT3 and anti-apoptotic proteins like Mcl-1 via dinaciclib." (PMID 39668430, 2024). "Similarly to the KRAS G12C-mutated CRC setting, BRAFV600E inhibition, in this CRC tumor context, showed an immediate upregulation of EGFR, this finding leading to the development of dual-blockade therapeutic strategies with the addition of an EGFR-directed monoclonal antibody." (PMID 39000083, 2024). "Given that tumors are heterogenous, particularly when metastasized and subjected to several lines of drug pressure, tumor cells harboring specific oncogenic mutations (i.e. KRAS) may confer EGFR-targeted mAb resistance to otherwise treatment-sensitive WT cells via paracrine signaling." (PMID 40727266, 2024).
tumor (continued). "Indeed, recent studies demonstrated that due to the intrinsic heterogeneity of intratumor, EGFR‐mutated NSCLC could seldom carry additional BRAF mutations, which is considered a predictor of resistance to EGFR inhibitors and tumor rapid progress." (PMID 38362771, 2024). "However, due to the tumor heterogeneity and small sample for EGFR detection, it is of great value to identify radiological features of patients with EGFR mutation and integrate the clinical variables into radiological characteristics to predict EGFR mutation before targeted therapy." (PMID 38528507, 2024). "Dexrazoxane may imitate the anti-tumor effects caused by EGFR and PI3K-Akt inhibitors." (PMID 38649770, 2024). "Interestingly, CR was observed in a patient whose tumor harbored an EGFR-activating mutation." (PMID 37646900, 2023). "Therefore, we proposed that MMP11 could cause tumor cell immune escape in EGFR-mutant LUAD by modifying the immune microenvironment." (PMID 36756152, 2023). "In NSCLC patients treated with the EGFR inhibitor gefitinib, patients with specific in-frame indel mutations in the EGFR gene were more sensitive to gefitinib, as these mutations increase the tumor’s dependence on growth factor signaling, compared to patients without such mutations." (PMID 38264526, 2023). "have shown that the activation of the EGFR pathway can upregulate the expression of PD-L1 and other immunosuppressive factors including cytokine production and accumulation of tumor-associated macrophages, suggesting that EGFR on NSCLC cell membrane could remodel the tumor microenvironment." (PMID 36910653, 2023). "Therefore, alternative approaches to prevent tumor progression in EGFR mutated patients are needed." (PMID 36875137, 2023). "Thus, for patients with both sensitizing EGFR mutations and extensive tumor-stroma interactions, additionally targeting HGF/MET may restore the response to EGFR TKIs." (PMID 36647832, 2023). "Therefore, HCP-LCE may be expected to cause milder side effects compared to EGFR high affinity binding antibodies such as cetuximab, for which the main side effect is skin toxicity, including rash, dry skin, hair growth disturbances and nail changes." (PMID 37081888, 2023). "However, a recent bicentric prospective study showed that aTAT of results (defined in that study as time from tumor sampling to initiation of EGFR-TKIs) was reduced by 12.5 calendar days when using the IdyllaTM EGFR Mutation Test versus NGS with a reported OPA of 96.4%." (PMID 36798672, 2023). "To investigate whether PAI-1 expression in the tumor tissue increased at the time of acquired resistance to EGFR-TKI, we compared the PAI-1 expression in the tumor specimens before and after acquired resistance to EGFR-TKIs in in patients with EGFR-mutated NSCLC." (PMID 36831438, 2023). "Recently, it was found that osimertinib could effectively treat LUAD with T790M mutation after resistance to first- or second-generation EGFR-TKIs3,12, however, osimertinib treatment could also endow the tumor with resistance to this drug and this resistance mechanism remains unknown." (PMID 37268635, 2023). "In addition, mutations in EGFR are also closely associated with radiotherapy resistance, with proliferation of tumour cells, DNA damage repair, hypoxia, and tumour metastasis formation being the four mechanisms, and DNA damage repair occupying an important position." (PMID 37542324, 2023). "Thus, our objective in the current study was to determine whether EGFR mutation was prognostic for tumor control or survival within the subgroup of patients who had undergone craniotomy." (PMID 36676186, 2023). "EGFR (also known ErbB1 or HER1) is overexpressed in 15%–30% of all BCs, most frequently in the aggressive triple-negative BCs (TNBCs) and inflammatory BCs, and it is also associated with large tumor size, poor differentiation, and poor clinical outcomes for these tumor types." (PMID 37498672, 2023).
tumor (continued). "Here we demonstrate that attention-based multiple-instance learning can predict EGFR mutational status in advanced metastatic lung adenocarcinoma samples directly from H&E images with state-of-the-art performance on real-world datasets, where many samples have less than 50% tumor content." (PMID 36927889, 2023). "However, more research needs to be devoted to the application of EGFR gene mutation or amplification in the treatment guidance and efficacy monitoring of other tumor types in the future which may even change the future treatment mode." (PMID 36701708, 2023). "Determined within tumor tissue by measuring mutations that are known to occur at a steady rate from a previously defined model, this requires further validation but implies a sizeable window of time for potential EGFR mutation screening and its co-occurring alterations." (PMID 37653450, 2023). "However, the tissue NGS from the independent organization demonstrated EGFR 19del positive with the same cancer tissue but different part with what we acquired, which implied the tumor heterogeneity may cause some “false positive” cases." (PMID 36599687, 2023). "Importantly, both clinical and proteomic data revealed patients harbored both EGFR mutations and amplifications exhibited higher values of the tumor proliferative marker Ki67, which implied the possible association between fast tumor cell proliferation and poor prognosis of these patients." (PMID 36720864, 2023). "The relevance of a deep analysis of tumor mutational profile in a study of METamp as a consequence of EGFR TKIs resistance therapies detected clones displaying METamp at a shallow frequency before any treatment with an EGFR TKI, suggesting that these clones were selected under therapeutic pressure." (PMID 36430388, 2022). "Furthermore, the EGFR mutation result was only determined by a part of tumor tissue, ignoring the heterogeneity of the entire tumor, which might be the reason for the inconsistent treatment outcome." (PMID 36052262, 2022). "Finally, to test the therapeutic potential of PEGylated SSNs as a tool for functional siRNA delivery in vivo, both SSNs and PEG-SSNs were electrostatically associated with EGFR siRNA and tested in 4T1 tumour-bearing mice for evaluating anticancer effects in a pre-clinical setting." (PMID 36412852, 2022). "Baseline EGFR T790M mutation detection in ctDNA might correlate with a larger baseline tumor size (56 mm for T790M (+) versus 39 mm for T790M (-); P < 0.0001) and a higher probability of extra thoracic metastasis [58% M1b for T790M (+) versus 39% M1b for T790M (-); P = 0.002]." (PMID 36387176, 2022). "However, a higher radiological severity score for LM could predict higher tumor cell counts in CSF, which would be associated with a higher detection rate of EGFR mutation." (PMID 35740489, 2022). "However, differences in the numbers of CD8+ T cells in the tumor, stroma, and tumor+stroma were found for some EGFR mutation subtypes; for example, more CD8+ T cell infiltration in the tumor was found in the EGFR G719A/C/S mutation group than in the 19del and S768I groups." (PMID 35265073, 2022). "PD-L1 expression heterogeneity between primary and metastatic tumours as well as dynamic fluctuations at different time points creates uncertainty in relying on tumour tissue expression of PD-L1 for treatment selection, particularly for patients whose tumours harbour EGFR mutations." (PMID 35372000, 2022). "However, the anti-tumor role of Fasudil in EGFR-mutation NSCLC as well as its mechanism are largely unknown." (PMID 36230634, 2022). "Since HER2 and EGFR both belong to the ErbB family and share similar downstream pathways, further researches could evaluate whether these two mutations play a similar role in immunogenicity, PD-L1 expression, and tumor microenvironment." (PMID 35980949, 2022). "The anti-tumor role of Fasudil in EGFR-mutation NSCLC as well as its mechanism are largely unknown." (PMID 36230634, 2022).
tumor (continued). "However, among other targeted therapies, tyrosine kinase inhibitors such as erlotinib or gefitinib are currently being used to treat NSCLC patients who have mutated or overactivated EGFR signaling in tumor cells, which play an important role in sustained cell proliferation." (PMID 35743223, 2022). "Two studies investigating tumor tissue or circulating DNA (ctDNA) of patients enrolled in the AURA3 trial associated this mutation in either blood or tissue samples with shorter progression-free survival (PFS) in patients who received first-line EGFR-TKI treatment." (PMID 35884398, 2022). "In addition, savolitinib treatment exhibited substantial anti-tumor activity in vivo (tumor regression: 35%) in the NSCLC cancer cell line NCI-H820 harboring an activating EGFR mutation (Ex19del), a gefitinib/erlotinib resistant mutation (T790M) as well as hyperactivated MET (data on file)." (PMID 36551608, 2022). "However, whether the clinical features such as age, sex, smoking, tumor stage, or EGFR mutational status contribute to TLSs heterogeneity is largely unknown." (PMID 35801360, 2022). "Therefore, this study aimed to determine if liquid biopsy could substitute tumor biopsy in detecting EGFR mutations and could be used to monitor disease progression in patients on afatinib therapy." (PMID 36192767, 2022). "Moreover,- since systemic administration of EGFR-BiTE could induce off-tumor toxicities - the local release by these CAR-T cells reduces the risk of cytotoxic T-cells activity on healthy tissues expressing EGFR." (PMID 35603195, 2022). "Thus, we suspected low TMB, low tumor infiltrating lymphocytes (TILs) and high Treg in patients with EGFR mutation may resulted in poor efficacy of IO of them." (PMID 35771151, 2022). "We also note that advances in quantifying the EGFR mutation in circulating tumor DNA after osimertinib treatment has the potential to quickly identify likely poor responding patients, who might be candidates for more aggressive treatment regimens such as those proposed in this study." (PMID 36969743, 2022). "In addition to EGFR-dependent mutations, an array of alternative EGFR-independent bypass signaling pathways may be concurrently activated to exacerbate tumor heterogeneity and therapeutic difficulty under EGFR-TKI treatment." (PMID 34319535, 2022). "Importantly, high levels of EGFR phosphorylation were detected in tumor tissues carrying EGFR-activating mutations (#12-T and #6-T), whereas minimal pEGFR was detected in the adjacent normal tissues and the tumor tissue without EGFR-activating mutation (#15-T)." (PMID 36376325, 2022). "Contrary to SCLC patients with rare mutations in epidermal growth factor receptor (EGFR), about 10~30% of NSCLC patients may harbor “activating mutations” in EGFR that causes constitutive activation of the EGFR pathway and provides the benefit of abnormal tumor growth." (PMID 35565351, 2022). "Subsequent frank tumor progression may then occur via the acquisition of other genetic events that further drive acquired resistance, such as drug-resistant secondary mutations in the EGFR or the activation of bypass signaling pathways." (PMID 35579943, 2022). "Given that these PI3K and MAPK signaling pathways are upregulated during resistance, we hypothesized that overexpression of DARPP-32 proteins in EGFR-mutated NSCLC may promote EGFR:ERBB3 “bypass signaling” that enables tumor cells to evade EGFR TKI monotherapy." (PMID 34675407, 2022). "For example, gefitinib cannot co-bind with JBJ-125 and is antagonistic in our biochemical assay but may nevertheless synergize with JBJ-125 via more potent inhibition of certain EGFR alleles that may arise due to tumor heterogeneity or in the context of EGFR amplification." (PMID 35534503, 2022). "However, the EGFR mutation S715I present in the tumor at 1.3% was detected in ctDNA at 4.4%." (PMID 36579573, 2022).
tumor (continued). "In addition to technical issues, EGFR T790M detection rate might be associated with different biological reasons, being tumour heterogeneity and low tumour burden." (PMID 35264788, 2022). "Activating mutations in the TKD of EGFR gene may be leading events in tumor development." (PMID 36467642, 2022). "However, whether the severity of LM on brain MRI correlates with the number of tumor cells in CSF and the EGFR mutation detection rate remains uncertain." (PMID 35740489, 2022). "In addition to single mutations, two or more different types of EGFR mutations may coexist in tumor cells, which accounts for approximately 4-14% of EGFR mutations." (PMID 36425553, 2022). "EGFR activity is also linked to chemotherapy resistance and cell survival under stress conditions, suggesting that the inhibition of EGFR associated with antineoplastic drugs might exert a synergistic effect on tumour progression." (PMID 34955078, 2022). "The subsequent tumor reduction could be predicted by the decreasing uptake of 18F-FDG on PET/CT scan as an early response to the initiation of TKI treatment for patients harboring EGFR-mutated NSCLC." (PMID 35515138, 2022). "Oncogenic signaling activated in a persistent tumor is inevitably affected by the tumor microenvironment; crosstalk between a persistent tumor and the tumor microenvironment, which may involve tumor-associated macrophages and cancer-associated fibroblasts, can contribute to EGFR-TKI resistance." (PMID 36612121, 2022). "Moreover, genetic and histological analysis of tumor biopsies from NSCLC patients with drug resistant tumors showed that all tumors maintained their original activating EGFR mutations and a fraction of them showed a pronounced epithelial-to-mesenchymal transition." (PMID 33922104, 2021). "Additionally, in-vivo studies showed that EGFR-directed TKIs may induce a switch from EGFR dependence to VEGFR signaling in tumor-associated endothelial cells which further shows the ineffectiveness of single-agent therapy." (PMID 33804477, 2021). "Given the strong evidence of the association between tumour infiltrating CD8 T-cells with responsiveness to immunotherapies, we wanted to further explore, in a larger cohort of patients, whether CD8 T-cells were depleted in tumours with EGFR oncogenic mutations." (PMID 35052732, 2021). "Therefore, in the present study, we assumed that the BN-based image features could also successfully quantify the intra-tumor heterogeneity and the low-intensity holes related with the EGFR mutations in the robust manner." (PMID 33428651, 2021). "At the same time, there was a clear trend for all mutated tumor samples collectively to show a colder phenotype compared to EGFR/ERBB2wt group (P = 0.068), the majority of which could be assigned to the immunological group of ‘hot’ tumors (17/26 = 65% versus 9/26 = 35%)." (PMID 34487971, 2021). "Furthermore, in a novel AlbuMus RAG1 knockout model (AlbuMus RAG1 KO) bearing EGFR-positive BRAF mutated tumours, we demonstrate superior anti-tumour effects after a single dose of the Albu-LiTE construct compared to a conventional Fc-less LiTE format and a full-length anti-EGFR monoclonal antibody." (PMID 33686177, 2021). "In order to uncover whether EGFR mutation would have an influence on tumor progression, we divided the researches collected in our analysis into two groups by the mutation status of EGFR, among which, two studies included only cases with gGGOs and were excluded in the following analysis." (PMID 34589430, 2021). "Analysis of tumor samples for correlation of fluorescence with EGFR IHC was found to be moderately associated (r = 0.48), but could be improved by weighting the intensities by the area fraction of EGFR expression." (PMID 34277418, 2021).